MAEL (maelstrom spermatogenic transposon silencer)
Description:
Plays a central role during spermatogenesis by repressing transposable elements and preventing their mobilization, which is essential for the germline integrity. Acts via the piRNA metabolic process, which mediates the repression of transposable elements during meiosis by forming complexes composed of piRNAs and Piwi proteins and governs the methylation and subsequent repression of transposons. Its association with piP-bodies suggests a participation in the secondary piRNAs metabolic process. Required for the localization of germ-cell factors to the meiotic nuage (By similarity).
Synonyms: FLJ14904; CT128; SPATA35
Tractability: No criterion of Open Targets' tractability assessment is met for any kind of drug.
Gene: Protein-coding gene on chromosome 1 (166,975,582 to 167,022,214, forward strand). Ensembl gene ENSG00000143194.
Subcellular location: Cytoplasm; Nucleus
Pathways (Reactome):
Gene expression (Transcription): PIWI-interacting RNA (piRNA) biogenesis
Gene Ontology:
Molecular function: sequence-specific DNA binding
Biological process: male meiotic nuclear division; negative regulation of DNA-templated transcription; piRNA processing; regulatory ncRNA-mediated gene silencing; spermatogenesis; regulation of miRNA-mediated gene silencing; transposable element silencing by piRNA-mediated DNA methylation
Cellular component: cytoplasm; nucleus; P granule; piP-body; autosome; chromatin; chromatoid body; perinuclear region of cytoplasm; XY body
Genetic constraint (gnomAD): Loss-of-function variants: 40 observed, 49.13 expected, observed/expected ratio (o/e) 0.81, 90% interval 0.63 to 1.06. The upper end of that interval is the gene's LOEUF score, 1.06, which puts it in group 4 of 6, group 1 being the genes least tolerant of losing a copy. Missense variants: 393 observed, 430.57 expected, observed/expected ratio (o/e) 0.91, 90% interval 0.84 to 0.99. Synonymous variants: 138 observed, 142.7 expected, observed/expected ratio (o/e) 0.97, 90% interval 0.84 to 1.11.
Homologues: Orthologues: chimpanzee MAEL (99% identical), macaque MAEL (98% identical), dog MAEL (93% identical), pig MAEL (92% identical), rat Mael (90% identical), rabbit MAEL (90% identical), mouse Mael (90% identical), guinea pig MAEL (81% identical), tropical clawed frog mael (42% identical), Drosophila melanogaster mael (18% identical).
Diseases named in the same sentence as MAEL in open-access papers:
MAEL is named in the same sentence as 34 diseases in open-access papers, as found by Europe PMC text mining. Sharing a sentence is not in itself a finding about the gene and the disease. The quoted sentences say what the papers report.
gastric cancer (4 papers, 2017 to 2022). A primary or metastatic malignant neoplasm involving the stomach. "Maelstrom (MAEL) is a cancer/testis-associated gene which is expressed in normal testis and also different tumor tissues such as colorectal and gastric cancers." (PMID 33902648, 2021). "Moreover, we demonstrated the oncogenic roles and underlying mechanisms of MAEL in gastric cancer." (PMID 29371914, 2017). "Based on our findings, MAEL overexpression contributes to the depression of ILKAP in gastric cancer." (PMID 29371914, 2017). "We have recently assessed the expression of MAEL in gastric cancer (GC) patients and showed that there was a correlation between MAEL expression and tumor size." (PMID 33902648, 2021). "Moreover, treatment with demethylating agents enhanced MAEL expression, suggesting that high MAEL mRNA level may result from DNA hypomethylation in gastric cancer." (PMID 29371914, 2017). "MAEL, also a CTAG, has been shown to be critical for cancer cell survival and is over-expressed in the bladder and gastric cancers." (PMID 34728792, 2022).
ovarian carcinoma (4 papers, 2014 to 2022). A malignant neoplasm originating from the surface ovarian epithelium. "The cancer-testis gene MAEL has been found to exert oncogenic effects in liver, bladder and colorectal cancers, but anti-oncogenic effects in ovarian cancer." (PMID 29371914, 2017). "In contrast to other cell systems, in vitro real-time invasion assay showed that over expression of piRNA pathway components such as PIWIL1 and MAEL has a repressive effect on ovarian cancer cell invasiveness." (PMID 24932571, 2014). "We examined the expression of piRNA pathway genes PIWIL1–4, MAEL and L1 in malignant EOC, benign tumors and normal ovary tissues, and also investigated possible roles of PIWIL1 and MAEL in ovarian cancer cell lines." (PMID 24932571, 2014). "PIWIL1 and MAEL were transiently over expressed in the ovarian cancer cell line SKOV3, followed by real-time measurements of cell invasiveness." (PMID 24932571, 2014). "In order to investigate the possible role of piRNA pathway genes in cancer progression, full-length PIWIL1 or MAEL transcripts were cloned and transfected transiently into the ovarian cancer cell line SKOV3 and assayed for invasiveness after 24 hrs of transfection." (PMID 24932571, 2014). "Furthermore, overexpression of PIWIL1 and MAEL suggests a role of these genes in reducing ovarian cancer cells invasiveness in vitro." (PMID 24932571, 2014). "However, the exact function and mechanisms by which MAEL acts in epithelial ovarian cancer (EOC) remain unclear." (PMID 35513870, 2022). "Lim and colleagues showed that piRNA pathway genes are overexpressed in ovarian cancer and they proposed that PIWIL1 and MAEL inhibit cell invasion." (PMID 26373553, 2015). "Since PIWIL1 and MAEL are up regulated in malignant EOC and expressed in the epithelial cells, we investigated if these two genes affect invasiveness of ovarian cancer cell lines that do not normally express these genes." (PMID 24932571, 2014).
bladder cancer (3 papers, 2020 to 2022). "In bladder cancer, MAEL plays a critical oncogenic role in supporting cell EMT and invasion and bladder cancer metastasis via downregulation of MTSS1 through DNMT3B." (PMID 35513870, 2022). "In addition, it has been reported that MAEL is highly expressed in a variety of cancer cell lines, including lung cancer, liver cancer, breast cancer, bladder cancer, and colorectal cancer." (PMID 35513870, 2022). "Finally, MAEL plays a key oncogenic role in bladder cancer by downregulating MTSS1." (PMID 33193734, 2020). "MAEL has different molecular mechanisms in different tumor types in which it activates the AKT/GSK-3b/SNAIL signaling in HCC, inhibits the E-cadherin in CRC, inhibits the MTSS1 in bladder cancer, and inhibits ILKAP tumor suppressor in GC." (PMID 33902648, 2021).
hepatocellular carcinoma (3 papers, 2014 to 2026). A malignant tumor that arises from hepatocytes. "The associations of MAEL with AKT activation and a suppressive TIME have been disclosed in the cell lines of hepatocellular carcinoma and esophageal squamous cell carcinoma." (PMID 38301040, 2024).
Azoospermia (2 papers, 2018 to 2019). Absence of any measurable level of sperm,whereby spermatozoa cannot be observed even after centrifugation of the semen pellet. "Interestingly, we identified meiotic proteins a priori unrelated to the UPS such as DAZL (deleted in azoospermia), SPAG1 (Sperm-associated antigen 1), SPATA5/20 (Spermatogenesis-associated protein 5/20), the tudor domain proteins TDRD1/6/9, MAEL (repressor of transposable elements), and RNF17." (PMID 31437213, 2019).
bladder urothelial carcinoma (2 papers, 2019 to 2021). "MAEL promotes the EMT process in bladder urothelial carcinoma via down regulation of metastasis suppressor 1 (MTSS1) which is associated with DNA methyltransferase (DNMT) 3B." (PMID 33902648, 2021). "It has been observed that the high levels of MAEL protein expression was correlated with advanced stages of tumor and poor survival in urothelial carcinoma of the bladder (UCB)." (PMID 33902648, 2021).
breast carcinoma (2 papers, 2016 to 2022). "One novel lncRNA, AC145110.1 on 8p12, was found differentially co-expressed with 127 mRNAs (including TOX4 and MAEL) in tumor and normal breast tissue and also highly correlated with breast cancer clinical outcomes." (PMID 27597120, 2016). "MAEL interacts with stress granule proteins and may be part of the ribonucleoprotein complex in breast cancer and colorectal cancer." (PMID 36476246, 2022). "MAEL is significantly highly expressed in breast cancer cells and related to some immune cells." (PMID 36476246, 2022).
colon cancer (2 papers, 2021 to 2022). "There was a direct correlation between MAEL expression and tumor aggressiveness in colon cancer which can be associated with suppressive role of MAEL in regulation of E-cadherin expression." (PMID 33902648, 2021). "MAEL expression is associated with cell proliferation and invasion of colon cancer cells." (PMID 36476246, 2022). "Furthermore, MAEL is over-expressed in various cancer types including lung, breast, prostate, and colon cancer." (PMID 36476246, 2022).
glioblastoma (2 papers, 2017 to 2024). The most malignant astrocytic tumor (WHO grade IV). "Among the 33 cancer types in the TCGA database (abbreviations), MAEL was expressed higher in TGCT, glioblastoma multiforme (GBM), brain lower-grade glioma (LGG), kidney renal papillary cell carcinoma (KIRP, also abbreviated as pRCC), and KIRC (also abbreviated as ccRCC)." (PMID 38301040, 2024).
lung adenocarcinoma (2 papers, 2017 to 2022). A carcinoma that arises from the lung and is characterized by the presence of malignant glandular epithelial cells. "The expression of MAEL was determined in lung adenocarcinoma (LUAD) based on GEPIA." (PMID 36476246, 2022).
lung carcinoma (2 papers, 2017 to 2022). "Therefore, we speculated MAEL may promote immune evasion in lung cancer." (PMID 36476246, 2022). "Therefore, MAEL may exert an oncogenic role in the progression of lung cancer." (PMID 36476246, 2022).
osteosarcoma (2 papers, 2019 to 2022). A usually aggressive malignant bone-forming mesenchymal neoplasm, predominantly affecting adolescents and young adults. "Besides, it promotes the proliferation and metastasis of osteosarcoma cells by sponging miR-618 and up-regulating MAEL expression." (PMID 36103025, 2022). "LINC00511 was confirmed to be beneficial for osteosarcoma development via sponging miR-618 and increasing MAEL expression and may thus be considered a potential target for osteosarcoma therapy." (PMID 31386627, 2019). "Our research explored the role of the LINC00511/microRNA-618/MAEL axis in osteosarcoma." (PMID 31386627, 2019).
benign ovarian tumors (1 paper, 2014). "Here we identified for the first time the increased expression of MAEL in malignant EOC and benign ovarian tumors." (PMID 24932571, 2014). "In order to investigate a possible role of this pathway in EOC, we performed semi-quantitative RT-PCR to investigate the expression of PIWIL1, PIWIL2, PIWIL3, PIWIL4 and MAEL in advanced stage serous EOC (n = 25), benign ovarian tumors (n = 19) and normal ovarian tissue (n = 8)." (PMID 24932571, 2014).
colorectal cancer (1 paper, 2017). A primary or metastatic malignant neoplasm that affects the colon or rectum. "Most cancer-testis genes are activated by DNA hypomethylation in cancer cells, and MAEL expression has been reported to be regulated by DNA methylation in breast and colorectal cancer." (PMID 29371914, 2017). "The cancer-testis gene MAEL is involved in the development and progression of bladder, liver and colorectal cancers." (PMID 29371914, 2017).
cystadenoma (1 paper, 2022). A benign or borderline cystic epithelial neoplasm arising from the glandular epithelium. "The results revealed overexpression of MAEL in 53% (76/143) of EOC specimens, 30% (6/20) of borderline tumor specimens, and 10% (3/30) of cystadenoma specimens, but no overexpression in normal ovarian tissues (p < 0.001)." (PMID 35513870, 2022).
gastric tumor (1 paper, 2017). "We verified the CpG island methylation of MAEL gene promoter among 4 pairs of gastric tumor and adjacent normal tissues and 8 gastric cell lines using pyrosequencing." (PMID 29371914, 2017). "Therefore, we verified MAEL mRNA expression using real time PCR and MAEL protein level using Western blotting in 4 pairs of gastric tumor and adjacent normal tissues and 8 gastric cell lines." (PMID 29371914, 2017).
glioma (1 paper, 2024). A benign or malignant brain and spinal cord tumor that arises from glial cells (astrocytes, oligodendrocytes, ependymal cells). "High MAEL expression was observed in TGCT, glioma, pRCC, and ccRCC." (PMID 38301040, 2024).
kidney chromophobe carcinoma (1 paper, 2024). "For instance, unlike pRCC and ccRCC originating from proximal tubular cells with high MAEL expression, kidney chromophobe carcinoma (KICH) develops from distal tubular cells that did not express MAEL and had far lower expression of MAEL than KIRC and KIRP." (PMID 38301040, 2024).
kidney tumors (1 paper, 2024). "Among the five cancer types with the highest MAEL expression, TGCT had equivalent expression levels of MAEL-206 and MAEL-202, while the MAEL expression in the other four cancer types was dominated by MAEL-206 (>90%), indicating the potential role of MAEL-206 in brain and kidney tumors." (PMID 38301040, 2024).
lentivirus infection (1 paper, 2022). Virus diseases caused by the Lentivirus genus. "For completeness, we stably overexpressed MAEL in MIHA and Huh7 cells through lentivirus infection." (PMID 35740546, 2022).
lymph node metastasis (1 paper, 2021). "There were also correlations between the levels of MAEL expression and tumor stage, grade, and lymph node metastasis." (PMID 33902648, 2021).
urothelial carcinoma of (1 paper, 2022). "Knockdown of MAEL significantly inhibits cell proliferation in urothelial carcinoma of the bladder cell lines." (PMID 36476246, 2022).
cancer (14 papers, 2014 to 2025). A tumor composed of atypical neoplastic, often pleomorphic cells that invade other tissues. "Of these cancers, only in ccRCC did MAEL expression appear to be associated with both recurrence-free survival (RFS) and overall survival (OS)." (PMID 38301040, 2024). "Of these cancers, only in ccRCC did MAEL expression exhibit associations with both recurrence-free survival and overall survival." (PMID 38301040, 2024). "As a novel cancer/testis-associated gene, MAEL is deemed to participate in stem cell self-renewal that favors tumor proliferation." (PMID 38301040, 2024). "Given the distinct expression patterns of MAEL isoforms in KIRC and TGCT, we further explored the DNA methylation level of MAEL and its association with mRNA expression in these two cancers." (PMID 38301040, 2024). "Maelstrom (MAEL), a novel cancer/testis-associated gene, may facilitate the initiation and progression of human malignancies, warranting comprehensive investigations." (PMID 38301040, 2024). "Given that MAEL was highly expressed and was associated with both RFS and OS in ccRCCs, we investigated its implications in this cancer type in depth." (PMID 38301040, 2024). "MAEL expression has been discovered by Northern blot in only the testis of normal human tissues, while it has been found to be aberrant in numerous cancer cell lines." (PMID 38301040, 2024). "Of note, we identified PTGS2 as a downstream target of MAEL and a key mediator of MAEL-dependent cancer stemness through AKT activation." (PMID 35740546, 2022). "Maelstrom (MAEL) is a cancer-testis (cancer-germline) gene, which is principally expressed in germline cells." (PMID 36476246, 2022). "Though MAEL-promoting tumorigenicity and metastasis are closely correlated with PI3K-AKT signaling, the molecular mechanisms of MAEL in regulating cancer stemness have remained unclear thus far." (PMID 35740546, 2022). "Recently, it has been suggested that MAEL is an oncogene and a potential therapeutic target for a variety of cancers." (PMID 35513870, 2022). "As a new candidate oncogene, MAEL’s precise molecular mechanism in promoting cancer progression has yet to be clarified." (PMID 35513870, 2022). "We demonstrated that MAEL positively regulates cancer stem-cell-like properties in HCC, and MAEL silencing provokes tumor cells’ sensitivity to sorafenib." (PMID 35740546, 2022). "Some of these pathway genes (PIWIL1, PIWIL2, TDRD1 and MAEL) are categorized as cancer/testis genes due to their restricted expression in testis but in recent years, have been observed to be aberrantly expressed in multiple cancers." (PMID 33374923, 2020). "As a cancer-testis (or cancer-germline) gene, MAEL is predominantly expressed in germline cells and is essential for meiosis and spermatogenesis under normal conditions." (PMID 31386627, 2019). "Abnormal activation of MAEL is also found in liver, colon and bladder cancers and contributes to tumorigenesis, cancer cell survival, invasion and epithelial-mesenchymal transition (EMT)." (PMID 29371914, 2017). "Our previous study demonstrated that MAEL is a cancer-testis gene that is only expressed in spermatocytes, round and early elongating spermatids in the testis, but is activated by demethylation in breast cancer cells." (PMID 29371914, 2017). "MAEL is known as a cancer/testis gene as it is expressed in testis and a number of cancer cell lines." (PMID 24932571, 2014). "Despite this experimental evidence elucidating the role of PIWIL1 and MAEL in cancer is difficult as differing effects are observed." (PMID 24932571, 2014). "MAEL regulated aggressive cancer features and the stem/progenitor cell characteristics of HCC." (PMID 35740546, 2022). "The maelstrom (MAEL) gene is a cancer-testis gene that is expressed in only spermatocytes." (PMID 31386627, 2019). "It is possible that MAEL regulates different pathways in different cancer types." (PMID 29371914, 2017). "MAEL is also a cancer testis gene regulated by DNA methylation." (PMID 27597120, 2016).
cancer (continued). "However, abnormal expression of MAEL has also been identified in multiple human cancer types." (PMID 31386627, 2019). "The oncogene role of MAEL and SND1 have been shown to enhance the development and maintain the stemness of carcinoma." (PMID 35083142, 2021). "Our comprehensive analysis revealed a more differentiated pattern where PIWIL1, MAEL and HENMT1 had increased expression, while PIWIL2, PIWIL4 and TDRD1 had decreased expression when comparing benign and malignant tumor samples." (PMID 33374923, 2020). "Nonetheless, many genes that have been described as targets of Dnmt3b in the mouse, including MAEL, SYCE1, and SYCP1, are aberrantly expressed in human cancers and are listed as cancer testes genes." (PMID 25198254, 2014). "Given the level of MAEL mRNA and its prognostic effect, MAEL may play a crucial role in KIRC, compared with other cancer types." (PMID 38301040, 2024). "The cancer microarray database on the Oncomine platform was searched to analyze the differential expression of MAEL mRNA between cancerous and noncancerous tissues." (PMID 29371914, 2017).